MMP9 (matrix metallopeptidase 9)
Diseases named in the same sentence as MMP9 in open-access papers (continued):
Sharing a sentence is not in itself a finding about the gene and the disease.
tumor (continued). "YFTL significantly reduced MMP-2, MMP-9, N-cadherin and Vimentin expression, but markedly increased E-cadherin expression in the tumor and lung tissues of tumor-bearing mice compared with the MC group." (PMID 30781674, 2019). "MMP-9 plays vital roles in cancer cell invasion and tumor metastasis, and regulates the expression and release of VEGF-1, which acts as a chemoattractant for invasion in the development of specific inhibitors." (PMID 31510010, 2019). "Other authors have described a gelatinase activity containing molecule of 130 kDa as Lipocalin-2/MMP-9 complex and contributed its function to inflammatory processes and tumour invasion." (PMID 31036020, 2019). "Both immunohistochemistry and qRT-PCR confirmed decreased MMP-9 and Madcam1 expression in tumor samples derived from cells in which MMP9 or Madcam1 were knocked down." (PMID 31600735, 2019). "Independent knockdown of MMP9 and Madcam1 in B16-F10 cells impeded epithelial-mesenchymal transition and inhibited subcutaneous tumor growth and formation of metastatic lung nodules in vivo." (PMID 31600735, 2019). "Overexpression of MMP-9 in different sample types has revealed the common feature of MMP-9 across a variety of tumor types, probably due to secretion of MMP-9 into body fluids." (PMID 33817161, 2019). "Specifically, among MMPs, MMP-2 and MMP-9 are most closely related to the invasion and metastasis of tumor cells." (PMID 31569766, 2019). "It has also been demonstrated that neutrophils TIMP-free MMP-9 regulate tumor angiogenesis and intravasation." (PMID 31799175, 2019). "Western blotting was used to quantitate the relative expression levels of MMP-2 and MMP-9 in mouse tumor tissues, and gelatin zymography was used to quantitate their enzyme activity levels." (PMID 31777578, 2019). "Like the phosphorylation of YAP principle, NF-κB entry into the nucleus reduced, and thus inhibiting MMP2 and the expression of MMP9 reaches inhibition of tumor cell invasion and metastasis." (PMID 31110076, 2019). "MMP-2 plays a significant role in angiogenesis and tumor formation, while MMP-9 is vital for metastasis and tumor development." (PMID 30708951, 2019). "MMP-9 has been found in large quantities in the cancer tissues and corroborates with the process of tumor cell invasion and metastasis." (PMID 30925799, 2019). "In summary, our data suggested that MTA2 was overexpressed in RCC tissues and cells and positively correlated with tumour grade and MMP-9 expression in vitro and in vivo." (PMID 31771219, 2019). "MMPs, especially MMP-2 and MMP-9 (both known as gelatinases A and B, respectively), are involved in several mechanisms contributing to cell adhesion and invasion, and further tumor progression." (PMID 31508793, 2019). "We found that matrix metalloproteinase 9 (MMP9) is an important component of the metastatic niche early in tumorigenesis and promotes circulating tumor cells to colonize the lungs." (PMID 31727800, 2019). "Western blot data showed that the protein levels of PCNA, CDK4, CDK6, Cyclin D1, MMP-2, MMP-9, and Bcl-2 were decreased, but cleaved caspase-3 was increased in tumor tissues of ApoE KO mice compared to those of WT mice." (PMID 31275318, 2019). "For example, α3β1 integrin activates MMP-9 synthesis through interaction with laminins and triggers reorganization of the actin cytoskeleton; α6β1 is involved in tumor invasion via activation of the urokinase plasminogen activator (uPA) receptor and MMP-2." (PMID 31344926, 2019). "Since MMP-9 plays a crucial role in angiogenesis and tumor invasiveness, we further assessed the effect of Sal-B treatment on tumor tissue level of MMP-9." (PMID 31726654, 2019). "Among which MMP9 has been shown to be involved in tumor invasion and metastasis, and its activity is significantly enhanced during tumor progression." (PMID 31346317, 2019).
tumor (continued). "MMP-9 seems to play a major role in tumor angiogenesis, through its critical intervention in the regulation of growth plate angiogenesis and recruitment of endothelial stem cells." (PMID 31886121, 2019). "Anti‐MMP9 antibody therapy significantly decreased ascites, tumour burden in pancreas and stomach, liver metastasis, spleen metastasis and total metastatic burden, as compared with controls." (PMID 30941918, 2019). "Production of several pro-metastatic factors is increased in the tumor microenvironment, including matrix metalloproteinase 9 (MMP9), vascular endothelial growth factor (VEGF), IL-8, and IL-6." (PMID 31477121, 2019). "This increase in MMP-9 expression in tumor tissue suggests that increased expression of MMP-9 is required for the disease to establish or spread." (PMID 31889941, 2019). "TANs contribute to the tumor invasion and angiogenesis through the production of matrix metalloproteinase-9 (MMP9), vascular endothelial growth factor (VEGF), and hepatocyte growth factor (HGF) in the primary and metastatic sites." (PMID 30691207, 2019). "MMP9 in the tumor microenvironment provides the conditions for tumor metastasis in a manner dependent on VEGFR-1." (PMID 31824776, 2019). "MMPs, especially MMP2 and MMP9, are known to take an important part in tumor growth, migration and invasion through degradation of extracellular matrix (ECM) and activation of growth factors." (PMID 31007650, 2019). "In contrast, “N2” neutrophils support tumor expansion by expressing arginase, MMP-9, VEGF, and numerous chemokines including CCL2, CCL5 and CXCL4." (PMID 30691207, 2019). "Among them, we discovered matrix metalloproteinases, such as MMP-2 and MMP-9, which are widely involved in tumor metastasis." (PMID 30931081, 2019). "MMP-2 and MMP-9 levels have been reported in correlation with local invasion, cervical nodal metastasis, tumor progression and prognosis of HNSCC patients." (PMID 30927923, 2019). "Enhanced expression of VEGF-A and other members of the VEGF family such as VEGF-C cause BECs to secrete MMP-9 and MMP-7 which help in remodeling of the basement membrane and surrounding ECM and promotes tumor metastasis." (PMID 31921870, 2019). "The results of our study are consistent with the present theory on the cellular origin of MMP-9, which claims that the tumor stroma is the main source of this protease." (PMID 31143300, 2019). "We focused our studies in MMP-2 and MMP-9 because they are related to invasive and metastatic processes, and a highly invasive capacity of tumor cells." (PMID 31671408, 2019). "NE has been shown to enter tumor cells and hyperactivate phosphatidylinositol-3 kinase while MMP-9 clears surrounding extracellular matrix to enable growth." (PMID 31416173, 2019). "In our study, the comparison of MMP-9 expression in the tumor stroma and in the perimatrix of the mucous membrane has demonstrated a statistically higher expression of the studied protein in the tumor stroma than in the perimatrix of healthy mucosa." (PMID 31143300, 2019). "Anti‐MMP9 antibody related changes in the expression of tumourigenic markers were further determined in tumour sections from AsPC‐1 PDAC peritoneal xenografts by IHC analysis." (PMID 30941918, 2019). "As MMP-2 and MMP-9 are key regulators of extracellular matrix (ECM) degradation and tumor invasion, CADM1 is therefore a metastasis susceptibility gene and is involved in the invasion-metastasis cascade in MM." (PMID 31334110, 2019). "MMP-9 expression was more significant in tumor stroma than in the perimatrix of the mucous membrane (p = 0.047)." (PMID 31143300, 2019). "NF-κB is the major inflammatory mediator, which also takes part in promoting tumour metastasis-related genes, including MMP-9, VEGF and iCAM." (PMID 30814922, 2019).
tumor (continued). "In vitro, incubation of 64Cu labeled Au NP with MMP-9 resulted in the cleavage of the peptide and distinct tumor accumulation properties of the contrast agent were observed between tumors with differing MMP-9 expression." (PMID 31315232, 2019). "In the case of MMP-9, statistically significant lower expression values were observed in stromal tissue (P=0.0445) in comparison to those in tumor tissue." (PMID 31223594, 2019). "In human gastric cancer, tumor cells were showed to make neutrophils produce MMP9, which significantly promoted angiogenic tube formation." (PMID 31616408, 2019). "Meanwhile, AF38469 increased T-cadherin expression, while decreasing the levels of N-cadherin, vimentin, and MMP-9 in subcutaneous tumor tissues." (PMID 30814514, 2019). "Functional analysis through shRNA-mediated stable knockdown of SMAD4 in microglia revealed the downregulation of the expression of matrix metalloproteinase 9 (MMP9), which has been shown to be involved in tumor progression and cell migration." (PMID 29861845, 2018). "In this report, we have shown, through multiple independent lines of evidence, that MMP-9 inhibition in preclinical mouse models can promote anti-tumor immunity by altering physical and biochemical properties of tumors relevant to effector T-cell trafficking." (PMID 30500835, 2018). "In particular, MMP-9, which plays vital roles in cancer cell invasion and tumor metastasis, is one of the most widely investigated MMPs." (PMID 30262739, 2018). "Neutrophils, whose phenotype has switched toward tumor promotion facilitate metastasis, angiogenesis via secretion of proangiogenic factors, such as MMP9 and VEGF and immunosuppression either directly or through the recruitment of regulatory T cells (Tregs)." (PMID 30349530, 2018). "Matrix metalloproteinases 2 and 9 (MMP-2 and MMP-9) are members of a family of zinc-dependent endopeptidases and contribute to the ability of tumor cells to degrade extracellular matrix components during tumor cell growth and metastasis." (PMID 29966255, 2018). "Taken together, 3 independent analyses—including gene-expression profiling, TCR sequencing, and flow cytometry—suggest that inhibition of MMP-9 reduces NeuT tumor growth in part by increasing T-cell diversity and memory/effector function." (PMID 30500835, 2018). "For some of these tumors, a unified antimetastatic mechanism regulated by the Kps/GPR54 system is related to the inhibition of the activity of the matrix metallo proteinase 9 (MMP-9) and the consequent blockade of tumor cell migration and invasion." (PMID 29662466, 2018). "Tumor associated N2 neutrophils are characterized by high expression of CXCR4, VEGF, and gelatinase B/MMP9 and can be induced on exposure to high TGF-β levels." (PMID 30304046, 2018). "Low pH has been shown to stimulate the release of Cathepsin B and MMP9, both of which accelerate tumor cell invasion." (PMID 29482580, 2018). "The correlation between CTHRC1 and MMP7 and MMP9 expression was further confirmed by IHC results obtained from 230 clinical NSCLC tumour samples." (PMID 29631554, 2018). "MMP-9-mediated proteolytic cleavage has been shown to activate various tumor-promoting cytokines such as IL-8 and IL-1β." (PMID 30500835, 2018). "MMP-9 degrades LN5 and prevents tumor-cell reversion; miRNAs’ ability to revert T4-2 cells is connected to inhibition of MMP-9 and the rescue of LN5." (PMID 29560860, 2018). "MMP9 is the most versatile of the MMPs and can degrade various elements of the tumour microenvironment, like elastin, fibrillin, laminin, gelatin and collagens of type IV, V, XI and XVI52,54." (PMID 29743718, 2018). "In somatotroph PAs, HEPN-1 silencing is associated with aggressive tumor behavior and is found to promote invasiveness via upregulation of MMP-2 and MMP-9 in GH3 and GT1.1 cells." (PMID 32922863, 2018).
tumor (continued). "This combined therapy of paclitaxel and curcumin decreases size of tumor and tumor cell proliferation with increased rate of apoptosis and downregulates MMP-9 expression." (PMID 29681985, 2018). "Matrix metalloproteinase-9 (MMP9) plays an important role in tumor invasion, and its expression was assessed by quantitative reverse transcription-PCR, Western blotting, and immunofluorescence." (PMID 30453504, 2018). "We also detected the proliferation-related molecules (Ki67 and PCNA) and the metastatic-related markers (MMP2 and MMP9) in the xenograft tumor tissues by Immunohistochemical staining." (PMID 30333480, 2018). "NF-κΒ upregulates proteins that promote tumor growth and proliferation, such as cyclin-D1, c-myc, MMP-9." (PMID 29467927, 2018). "Increased acidity causes activation of matrix metalloproteinase-9 (MMP-9) and enhances epithelial mesenchymal transition (EMT) of neighboring cancer cells, positively affecting tumour progression." (PMID 29967776, 2018). "MMP9 is able to degrade type IV collagen, thereby facilitating stromal and vascular invasion by tumor cells." (PMID 30013825, 2018). "MMP-9 can also promote the tumor cells to move forward by interacting with the integrins on the surface of the cells and modulating its function." (PMID 30046339, 2018). "In the tumor-free intestinal tissue extract analyses, baseline MMP-9 levels had a median concentration of 7.1 ng/mL (13.4), range 2.6–34.0 ng/mL." (PMID 29520667, 2018). "Previous reports showed that radiation enhanced MMP-2 and MMP-9 secretion and activity, which enhanced tumor aggressiveness and promoted tumor metastasis." (PMID 30359388, 2018). "Here, we found that the transcriptomic profiling of NB-MSCs isolated from tumor samples derived from NB patients was enriched in EMT-associated genes compared to BM-MSCs, in particular in CDH2 and MMP-9 genes." (PMID 30482160, 2018). "The strong anti–MMP-9 efficacy observed precluded the assessment of the combined anti–MMP-9/anti-PDL1 impact on tumor growth." (PMID 30500835, 2018). "For instance, MMP-9 has been found to play a role in tumor invasion, metastasis and angiogenesis and to mediate tumor microenvironment." (PMID 30262739, 2018). "Excessive M2 macrophages release MMP2 and MMP9 that can specifically degrade the extracellular matrix, thereby promoting the migration of tumor cells and tumor stromal cells." (PMID 29329591, 2018). "Neutrophils can also release oncostatin M and matrix metalloproteinase (MMP-9) to induce production of vascular endothelial growth factor, which can promote angiogenesis and invasion of tumor cells in multiple cancer models." (PMID 30473691, 2018). "Consistent with the ELISA data, CTHRC1 expression was significantly correlated with MMP7 and MMP9 expression in primary tumour tissues." (PMID 29631554, 2018). "MMP-9 levels in the tumor-free tissue extracts had increased to baseline (median values 7.1 and 8.1 ng/mL, respectively; p < 0.01)." (PMID 29520667, 2018). "It has been observed that hypoxia-induced upregulation of MMP2 and MMP9 in breast and colon cancer cells contributed to tumor cell invasion and a membrane-bound form of MMP—MT1-MMP (MMP-14) is also induced via hypoxia in breast and renal carcinoma cells." (PMID 30356678, 2018). "The mRNA levels of MMP-9 increased in patients aged≥45 years (P = 0.015), those with lymphovascular invasion (P = 0.003), and higher tumor stages (III and IV) (P = 0.011)." (PMID 30509240, 2018). "Although proteinases are commonly expressed by stromal cells, epithelial expression of MMP-9 or MMP-14 in tumor cells has been correlated with decreased patient survival." (PMID 29393911, 2018). "The present study showed that SE1 from seahorse obviously inhibited tumor metastasis and MMP-9 expression by PMA induced in HT1080 cells." (PMID 30519264, 2018). "It has been suggested that MMP9 released from these cells promotes angiogenesis and tumor progression." (PMID 30262908, 2018).
tumor (continued). "The percentage of area of MMP-9 staining was increased 5-fold (p=0.012) at the invasive front compared to the tumor core." (PMID 29731961, 2018). "As the invasive ability of tumor cells is often correlated with the production of secretory proteases, the effect of HDGF knockdown on the expression of tumor invasion-associated secretory proteases MMPs including MMP2 and MMP9 were determined." (PMID 29300772, 2018). "MMP-9, a member of the MMPs, has long been postulated to play an important role in poor prognosis in tumour cells." (PMID 30142200, 2018). "Nosso objetivo foi avaliar a associação entre o polimorfismo da 1562 C/T (rs 3918242) do gene MMP-9 e o desenvolvimento da neoplasia mamária." (PMID 30352460, 2018). "MMP-9 can promote tumor cell proliferation by releasing the cell-membrane-bound precursors of some growth factors." (PMID 30046339, 2018). "Secretion of active MMP2 and MMP9 into the stroma of primary tumors allows for break-down of the surrounding tumor matrix and matrix remodeling to promote epithelial cell invasion." (PMID 30458886, 2018). "Our results confirmed the markedly elevated expression of MMP-10 and MMP-9 in the tumor lesions of ApoE−/− mice compared to that in WT mice." (PMID 29458390, 2018). "MMP9, on the other hand, was shown to promote tumor formation when expressed in stromal cells but also correlated with favorable prognosis for patients when expressed in carcinoma cells." (PMID 30174795, 2018). "Concerning MMP-9, a general trend was observed in all of the groups, showing a production peak two days after tumor induction and decreasing levels of this molecule were then detected in the following weeks." (PMID 30305693, 2018). "Apelin stimulation also induced expression of APJ receptor and matrix metalloproteinase-1 (MMP-1), matrix metalloproteinase-9 (MMP-9), IL-1, and IL-6, which are associated with tumor invasion and metastasis." (PMID 29875677, 2018). "Various signaling molecules and cytokines such as OPN, VEGF, Flk1, Cox2 and MMP-9 play an important role during process of tumor angiogenesis and metastasis." (PMID 29310608, 2018). "Recent studies have shown a correlation between increased MMP2/MMP9 gene expression in tumour tissues and clinical status, histopathological grading, and metastasis occurrence." (PMID 30595764, 2018). "MMP9 degrades type IV collagen and plays important roles in various pathophysiological processes, such as wound healing, tumor invasiveness and progression." (PMID 29632659, 2018). "Neutrophils, for example, through the secretion of MMP9 and G-CSF, favour the metastatic capacity of tumor cells." (PMID 30333826, 2018). "To evaluate the mechanism of action of anti–MMP-9 with regard to T-cell signaling signatures, we assessed the repertoire of tumor-infiltrating T cells by TCRβ sequencing." (PMID 30500835, 2018). "In summary, our results showed that SE1 reduces the metastatic ability of tumor cells by blocking expression and activities of MMP-9 and this was related to the downregulation of the NF-κB and p38 and JNK signaling pathways." (PMID 30519264, 2018). "By exploring the contribution of stromal cell-released MMP9 to ovarian tumor growth, a former study showed that cancer cells can change macrophage secretion of cytokines, chemokines, MMPs to enhance tumor growth in peritoneal cavities of nude mice." (PMID 28929459, 2018). "In summary, these results suggest that ALT-C binds to α2β1 integrin in tumor cells and inhibits MMP-9 and MMP-2, but upregulates c-Myc (mRNA level)." (PMID 29713337, 2018). "Both MMP2 and MMP9 have been reported to function in tumor cell invasion, thus leading to metastasis." (PMID 30587839, 2018). "MMP2 and MMP9, in particular, have the ability to cleave type IV collagen, the main component of the basement membrane, and contribute to the metastasis of tumor cells." (PMID 29844876, 2018).